EGFR (epidermal growth factor receptor)
Diseases named in the same sentence as EGFR in open-access papers (continued):
Sharing a sentence is not in itself a finding about the gene and the disease.
breast carcinoma (continued). "We found an inverse correlation between EGFR expression and miR-218 levels in cell lines and primary breast cancer tissues." (PMID 37088795, 2023). "Other researches show that activated PROC-PROCR-F2R axis can stimulate the MAPK pathway via activation of epidermal growth factor receptor (EGFR) to promote the progression of breast cancer." (PMID 37274740, 2023). "A significant correlation was found between mRNA abundance of c-MET and EGFR in breast cancer patients, and the concurrent overexpression of these genes was associated with comparatively poorer overall survival outcomes (p<0.0001)." (PMID 37924112, 2023). "In our study, we identified a novel regulation mechanism by which PELI1 and EGFR cooperate to promote breast cancer metastasis." (PMID 36841821, 2023). "The peculiarity of this venom-isolated peptide is that it binds to the epidermal growth factor receptor (EGFR), which characterizes breast cancer in more than half of patients with this disease." (PMID 37046428, 2023). "EGFR is positively correlated with PELI1 expression in breast cancers, and its activation led to the phosphorylation of PELI1 at Tyr154 and Thr264, which subsequently activated its E3 ubiquitin ligase." (PMID 36841821, 2023). "Clinical trials have demonstrated that the EGFR inhibitor, lapatinib, can modestly increase the survival time of breast cancer patients and exhibit antitumor efficacy." (PMID 37470034, 2023). "In vitro studies have demonstrated that treating breast cancer and pancreatic cancer cells with high glucose results in molecular changes such as phosphorylation of the epidermal growth factor receptor (EGFR), which promotes cancer cell proliferation." (PMID 37511575, 2023). "TLK2 enhances the aggressiveness of breast cancer through the activation of the EGFR/SRC/FAK signaling pathway." (PMID 38343446, 2023). "In this work, two breast cancer biomarkers were selected to develop sensors for cancer diagnosis, and these are the human epidermal growth factor receptors 1 and 2 (HER-1 and HER-2)." (PMID 36979567, 2023). "We employed antibodies of IgG1 or IgG2 isotypes against the tumor associated antigens EGFR and HER2 to demonstrate that sialic acid reduction on breast carcinoma cells enhanced ADCC activity mediated by PMN." (PMID 37346044, 2023). "Cetuximab is a monoclonal antibody targeting epidermal growth factor receptor (EGFR) for inhibiting the EGF signaling pathway in breast cancer." (PMID 37900279, 2023). "PTPH1 can also dephosphorylate EGFR in breast cancer cells and disrupt EGFR interaction with ER in the cytoplasmic membrane and thereby sensitize breast cancer cells to EGFR inhibitor lapatinib." (PMID 37443708, 2023). "This pattern is consistent with the tumor-suppressor effect of TGFβ on primary tumor formation and its subsequent conversion to a promoter of metastatic growth, and the paradoxical effect of EGFR during breast cancer progression." (PMID 37463901, 2023). "Researchers have discovered that the activation of FAK and JNK regulates RAB27A-mediated exocytosis, facilitating the secretion of the EGFR, which in turn promotes migration and invasion in breast cancer." (PMID 37685910, 2023). "It is suggested that BRE reversed drug resistance of breast cancer through EGFR inhibition of P‐gp expression." (PMID 37584258, 2023). "It was reported that ERK activation by EGFR is required for preventing anoikis in Her2-positive breast cancer cells." (PMID 37866630, 2023). "TLR3 plays a negative regulatory role in the initiation and progression of human breast cancer cells, at least in part by downregulating the EGFR/PI3K/AKT pathway." (PMID 37005579, 2023). "The studies using breast cancer cell lines overexpressing HER2 provide us with the result that GEF is selective for EGFR in vitro, but at the same time, in vivo, it reduces the basal phosphorylation of EGFR1, EGFR2, and EGFR3." (PMID 38090376, 2023).
breast carcinoma (continued). "We previously demonstrated that the WAP-TGFα transgenic mouse model is sensitive to knockout of the retrograde driver, Muc1, highlighting its use as a model of EGFR-dependent breast cancer." (PMID 36253541, 2023). "HER2 is an important receptor and onco-marker that belongs to the epidermal growth factor receptor (EGFR) family and is overexpressed by 15–30% in breast cancer." (PMID 37175137, 2023). "In triple negative (ERα‐, PR‐, HER2‐) breast cancer cell lines, ERα‐36 promotes proliferation via rapid epidermal growth factor receptor (EGFR)‐extracellular signal‐regulated kinase (ERK) signalling." (PMID 36510342, 2023). "Our data showed that knockdown of PELI1 enhanced the sensitivity of EGFR inhibitor against the EMT in breast cancer cells through a decrease of EGFR levels, suggesting that co-inhibition of PELI1 and EGFR have a synergetic effect with EGFR-TKI." (PMID 36841821, 2023). "We took the three targets with highest predicted probability; ERBB4 (0.790), EGFR (0.784) and ERBB2/HER2 (0.724) all known to be expressed in HER2 + breast cancer, to the causal reasoning analysis stage." (PMID 37715141, 2023). "This can be understood by knowing that co-expression of EGFR and its respective ligands has been found in these breast cancers, which indicates that an autocrine loop mechanism functions in these cancers." (PMID 38090376, 2023). "EGFR has been especially studied in breast cancer, as it is an important target for the development of new treatment." (PMID 37880270, 2023). "The discovery of highly effective EGFR inhibitors is of paramount importance in the treatment of tumors, including lung cancer, cervical cancer, and breast cancer." (PMID 38005329, 2023). "The nanocomposite was used for intracellular Raman visualizationof epidermal growth factor receptor (EGFR) that is overexpressed inMCF-7 breast cancer cells." (PMID 37556357, 2023). "Secondly, although EGFR is observed in typical epithelial cells, it is excessively expressed in many epithelial tumors including breast cancer, which has been related to worse clinical output in several patients." (PMID 38090376, 2023). "GREM1 has also been reported to bind to and activate epidermal growth factor receptor (EGFR) in SKBR3 human breast cancer cells that overexpress HER2/EGFR." (PMID 37615860, 2023). "Studies also found that the knockdown of HER3 expression is more effective in inhibiting breast cancer cell growth than the knockdown of EGFR." (PMID 37947595, 2023). "By identifying ~104 complexoforms from 17 protein complexes, our nTDP approach revealed several molecular features of the breast cancer proteome, including EGFR-induced dissociation of nuclear transport factor 2 (NUTF2) assemblies that modulate ER activity." (PMID 37546719, 2023). "We now show that such a modified peptide, cSNX1.3, can function as a therapeutic in an EGFR-dependent model of breast cancer and block RTK-induced migration and cell survival." (PMID 36253541, 2023). "Conditionally activated EGFR (V-Erb-B : ER) is one of the reasons for drug resistance in breast cancer cells." (PMID 38090376, 2023). "EGFR is typically used as a potential therapeutic target for TNBC since it is frequently overexpressed in TNBC compared to other breast cancer subtypes." (PMID 36672350, 2023). "Here, we constructed hybrid HBc-GE11 VLPs, which presented GE11 peptide to target EGFR+ breast cancer." (PMID 37020877, 2023). "Upregulated EGFR/MEK1/MAPK1/2 signaling also occurs in 4-hydroxytamoxifen-resistant MCF-7 breast cancer cells and blocks BimEL-dependent apoptosis." (PMID 37575061, 2023). "Overexpression of HER2, a transmembrane glycoprotein related to the epidermal growth factor receptor, results in a biologically and clinically aggressive breast cancer subtype." (PMID 37686984, 2023).
breast carcinoma (continued). "We evaluated the efficacy of cSNX1.3 in tumor-bearing WAP-TGFα transgenic mice (an EGFR-dependent model of breast cancer), where cSNX1.3 treatment resulted in significant tumor regression without observable toxicity." (PMID 36253541, 2023). "Conversely, EGFR was most prominently expressed in high-grade ER-negative samples in our study and is a known marker of poor prognosis in breast cancer." (PMID 37088795, 2023). "LUBAC inhibitor HOIPIN-8 inhibits breast cancer cell proliferation and clone formation by blocking EGFR-mediated NF-κB activation." (PMID 37525118, 2023). "Targeting of EGFR with specific inhibitors has been investigated as a possible treatment strategy for certain subtypes of breast cancer." (PMID 37885828, 2023). "At present, a variety of EGFR inhibitors targeting TNBC are used in the clinical treatment of breast cancer, such as the tyrosine kinase inhibitors afatinib, erlotinib and lapatinib, as well as monoclonal antibodies such as cetuximab and panitumumab." (PMID 37670360, 2023). "Another EGFR that is co-expressed in overexpressing EGFR2 breast cancer is EGFR3, and these cancers exhibit higher concentrations of phosphotyrosine on EGFR3 due to the spontaneous dimerization of EGFR2 with EGFR3." (PMID 38090376, 2023). "CD44 is a surface marker of CSCs and has been reported to act as a co-receptor for EGFR that activates downstream signaling in breast cancer." (PMID 37924112, 2023). "Another study found that EGFR overexpression resulted in higher rates of lung metastasis in mammary tumors when compared to tumors with lower EGFR expression." (PMID 36831661, 2023). "Reports also indicated decreased expression of ErbB receptors such as EGFR, HER2, and HER3 to NDRG1 expression preventing the formation of HER2/HER3 dimers and disrupting major oncogenic pathways primarily associated with mammary tumors." (PMID 37970212, 2023). "For example, autophagy-related gene Beclin 1 decreases in breast cancer, and its downregulation will promote epithelial mesenchymal transition and reduce the inhibitory effect on EGFR, thus promoting the growth and migration of breast cancer." (PMID 35692501, 2022). "Previous studies have found that HOXB5 is up-regulated in breast cancer and can enhance tumor growth via the Wnt/β-catenin pathway, and its transcriptional activation of EGFR promotes tumor cell invasion." (PMID 36443670, 2022). "For example, some studies indicated that VIP/VIPR1 signaling stimulates transactivation of HER2 and EGFR in human breast cancer." (PMID 35864952, 2022). "FEN1-mediated DNMT3a up-regulation, released the suppression of its targeting MET and EGFR, and promoted breast cancer cell proliferation by activating PI3K/AKT and MAPK/ERK pathways in MCF-7cells." (PMID 35620052, 2022). "Previous studies have shown that dimerization of EGFR and HER2 leads to the rapid activation of downstream kinases, such as Akt, PCK−α, and ERK1/2−MAPK, leading to the loss of ER−α expression in breast cancer cells." (PMID 36232636, 2022). "MET CNA has been reported to be associated with resistance to anti-HER2 TKIs in EGFR-mutant NSCLC, HER2-amplified breast cancer, and HER2-mutated NSCLC." (PMID 35101045, 2022). "Breast cancer cells overexpress the EGFR protein and EGFR exhibits membrane-bound and nuclear signaling activities." (PMID 35745583, 2022). "EGFR is more frequently overexpressed in TNBC than in other breast cancer subtypes, and EGFR expression has been acknowledged as a weak prognostic marker for TNBC." (PMID 36188649, 2022). "Our findings showed that such TGFα-EGFR carcinogenic action can be enhanced in breast cancer with low expression of WWOX tumor suppressor gene which is supposed to be a very common event in this tumor." (PMID 35290621, 2022). "Using siRNA to knockdown the expression of EGFR genes can suppress the growth of breast cancer cells." (PMID 35517864, 2022).
breast carcinoma (continued). "The results indicated that FABP5 and PPARβ/δ were the key mediators of EGFR’s ability to enhance cell proliferation, further confirming that PPARβ/δ acted as a tumor-promoting factor playing a role in breast cancer." (PMID 36611922, 2022). "For example, targeted therapies have established intracranial activity in patients with Her2-positive breast cancer BM, ALK-rearranged or EGFR-mutated NSCLC BM and for BRAF V600E mutated melanoma BM." (PMID 36605448, 2022). "The compound C2 displayed better anticancer activity against the panels of CNS, melanoma, ovarian, prostate, and breast cancer cell lines than curcumin and other anti-EGFR agents gefitinib and imatinib in single dose assay." (PMID 36297760, 2022). "The EGFR protein concentration was also reduced in breast cancer (MCF-7) more than in the lung adenocarcinoma cell line (A549)." (PMID 36457709, 2022). "In breast cancer, EGFR is an alternative survival pathway that becomes activated in tamoxifen-treated cancers to mediate resistance to the drug and promote ongoing cancer progression." (PMID 35454796, 2022). "EGFR is frequently overexpressed in basal-like breast cancers, which comprises most TNBCs, and this overexpression is associated with metastasis progression and poor clinical outcome." (PMID 36380366, 2022). "The targeting moiety used here was a short peptide that can target EGFR overexpressed breast cancers." (PMID 35160746, 2022). "CD73 siRNA-containing liposomes were targeted with GE11 peptide against EGFR and its tissue biodistribution was evaluated in 4T1 breast cancer mouse model." (PMID 35729230, 2022). "For example, consider the anti-breast cancer drug Trastuzumab which binds to the epidermal growth factor receptor HER2, expressed at very high levels in some breast cancers." (PMID 35360890, 2022). "Erlotinib and gefitinib, which bind selectively to ATP-binding sites of EGFR, have been so far the only two single-target TKIs, whereas lapatinib, the first TKI approved for breast cancer shows equal activity toward EGFR and HER2." (PMID 35295841, 2022). "The overexpression of EGFR facilitates PR function, which then effectively promotes breast cancer progression." (PMID 36144225, 2022). "The dual tyrosine kinase (EGFR/HER2) inhibitor lapatinib is currently used to clinically treat HER2-positive breast cancer." (PMID 36090218, 2022). "To summarize, TGFα-EGFR is regulated in breast cancer mostly by estradiol through ERα regulation of TGFα expression." (PMID 35290621, 2022). "Similar to EGFR, overexpression of HER2 in tumors, mainly human breast carcinoma, is associated with more aggressive disease and poor prognosis." (PMID 35456655, 2022). "This method has made progress not only in the identification of EGFR status or breast cancer but also in gastrointestinal tumors, gliomas, reproductive system tumors, respiratory system tumors, etc.." (PMID 35663041, 2022). "Since EGFR and FN are considered clinically relevant exosome protein markers for breast cancer, the expression of EGFR and FN in the conditioned medium was examined." (PMID 35053535, 2022). "We also used the drug-oligonucleotide conjugates to investigate the localization of drug binding in formalin-fixed healthy human colon tissue, expressing quite low EGFR levels, and in fresh-frozen breast cancer tissue." (PMID 36189884, 2022). "Similar observations have been made in isogenic cell models and breast cancer tissues derived from female patients, with a strong correlation between EGFR expression and resistance to EGFR inhibitors." (PMID 36380366, 2022). "ERBB2, a member of the ERBB family of receptor tyrosine kinases (RTKs) (EGFR/ERBB1, ERBB2, ERBB3, and ERBB4), is overexpressed in approximately 15–20% of human breast cancers and its expression is highly associated with poorer overall survival." (PMID 35431974, 2022).
breast carcinoma (continued). "Exosomal donor cells were engineered to secrete GE11 peptide modified exosomes (GE11-exosomes), and the tumor inhibitory miRNA was transferred to breast cancer tissue with high expression of EGFR by exosomes." (PMID 34973131, 2022). "EGFR is a transmembrane receptor, and its overexpression has been observed in breast cancer tissues and cell lines, and EGFR silencing inhibits cancer cell proliferation." (PMID 36483592, 2022). "This phenomenon is possible by binding anti‐epidermal growth factor receptor (EGFR) antibodies to MS2 VLPs to target EGFR on breast cancer cells in the HCC1954 cell lines." (PMID 35916145, 2022). "Biomarkers (e.g. estrogen receptor status in breast cancer, epidermal growth factor receptor (EGFR) status in lung adenocarcinoma, mismatch repair in colorectal cancer) are frequently reported by pathologists that do not finalize the case." (PMID 35333879, 2022). "Lapatinib is one of tyrosine kinase inhibitors targeting epidermal growth factor receptor (EGFR/ErbB1) as well as HER2/ErbB2 specifically for treating HER2+ subtypes of breast cancer." (PMID 36936274, 2022). "Epidermal growth-factor receptor (EGFR) is overexpressed in 15–70% of breast cancer, and thus, is an attractive candidate for dual targeting alpha therapy." (PMID 36733936, 2022). "Berberine has demonstrated to inhibit the breast cancer cells migration by inhibiting IL-8 transcription in an EGFR-dependent way." (PMID 35559258, 2022). "As shown in previous studies, S1P either directly transactivated EGF receptors (EGFR) in gastric cancer cells or was responsible for upregulating EGFR in lung or breast cancer cells, contributing to tumour progression." (PMID 35806446, 2022). "mPRα activation also results in activation or inhibition of EGFR signaling in lung and breast cancer cells." (PMID 35681480, 2022). "In breast cancer, EGFR is overexpressed in approximately half of triple-negative breast cancer (TNBC) and inflammatory breast cancer (IBC) patients." (PMID 35663041, 2022). "It has been demonstrated in a model of breast cancer that FAM83A acts downstream of the EGFR signaling and exerts oncogenic properties by promoting tumor growth, and conferring resistance to EGFR-tyrosine kinase inhibitors." (PMID 35205751, 2022). "Gefitinib works against breast cancer through attaching to the ATP-binding site of the EGFR protein." (PMID 36457709, 2022). "Kinases were applicated to the clinic strategy, such as anti-EGFR (abemaciclib) in breast cancer, and anti-MAP2K1 (trametinib) in melanoma." (PMID 35397555, 2022). "Similar to other cell lines, metformin also induces AMPK activation, reduced the phosphorylation of epidermal growth factor receptor (EGFR), mitogen activated protein kinases (MAPKs) and Src and lowered the levels of cyclins D1 and E in breast cancer cells." (PMID 35574410, 2022). "The development of cutaneous vasculitis and formation of ANCA was described in breast cancer patients treated with EGFR inhibitors." (PMID 35457163, 2022). "Targeted delivery of immRNA‐loaded RBCEVs conferred improved specific anti‐tumour immune response in EGFR‐positive metastatic breast cancer mouse models." (PMID 35430766, 2022). "This status is rare as we have typically observed, across the breast epithelial and breast cancer samples we have profiled, that EGFR and ERBB2 activity are often jointly active or inactive, consistent with the obligate dimer behavior of ERBB2." (PMID 35879309, 2022). "BRK activates EGFR tyrosine kinase signals and leads to upregulation of cell growth and migration in breast cancer." (PMID 36017236, 2022). "Overexpression of HER3 is often associated with overexpression of HER2 and/or EGFR, playing an important role as co-receptor in HER2 + breast cancer and in a subset of EGFR-positive lung tumors." (PMID 36271429, 2022).